TIGIT (T cell immunoreceptor with Ig and ITIM domains)
Diseases named in the same sentence as TIGIT in open-access papers (continued):
Sharing a sentence is not in itself a finding about the gene and the disease.
tumor (continued). "The study authors observed that the number of intra-tumoral TIGIT positive cells outnumbered CD8+ T cells, indicating that other immune cells (including NK cells) might be suppressed within the tumor microenvironment via this checkpoint." (PMID 33317028, 2020). "Notably, TIGIT is highly expressed in CD8+T cells, CD4+T cells, and NK cells during tumor infiltration." (PMID 33490104, 2020). "TIGIT is expressed on both activated T and NK cells and interacts with two specific DNAM-1 (CD226) ligands, CD155 (PVR) and CD112 (nectin-2), which are expressed on both immune and tumor cells." (PMID 32610578, 2020). "Notably, some antagonistic Abs (e.g., anti-TIGIT and anti-NKG2A mAbs) can induce potent anti-tumor immunity via the recovery of the functions of both NK and T cells, thus revealing extraordinary potential in cancer therapy." (PMID 32714324, 2020). "Therefore, TIGIT, CD96, and CD155 are deemed as key immune checkpoints for NK cells, and the blockade of these molecules has shown great promise in tumor immunotherapy." (PMID 32714324, 2020). "First, we did not assess the development of immune memory in tumor‐bearing mice treated with anti‐TIGIT." (PMID 32212317, 2020). "Using a xenograft model of human melanoma, it was shown that tumour-specific T cells expressing a hybrid molecule containing the TIGIT extracellular domain fused to the CD28 intracellular domain displayed enhanced production of IFN-γ and TNF-α and improved tumour control." (PMID 32708397, 2020). "TIGIT/PVR ligation could disrupt the granule polarization and cytotoxicity of NK cells and suppress the anti-virus and anti-tumor activity of CD8+ T cells." (PMID 32894141, 2020). "We reason that the effect of anti-TIGIT: mIgG2a and FcγRIV can be investigated in the context of anti-tumor response without perturbing the cellular composition of TME with such an approach." (PMID 33117369, 2020). "Their study measured functional exhaustion of NK cells, extracted from tumor-bearing mice, through the expression of IFN-γ, TNF, CD107a, and cytotoxic molecule TRAIL, noting a reduction in expression of these markers which was restored through TIGIT blockade." (PMID 32532329, 2020). "TIGIT blockade alone or with PD-1/PD-L1 or TIM-3 could significantly restore the function of CD8+ T cells and inhibit tumor growth in both tumor models and clinical trials." (PMID 32894141, 2020). "With the elevated secretion of IFN-γ after TIGIT blockade, expression of PD-1 on CIK cells and PD-L1 on both CIK and tumor cells could also be detected to further develop the cytotoxicity profile of CIK cells by immune checkpoint blockade." (PMID 32882824, 2020). "Recently, the physiological functions in tumor surveillance of NK cells, as well as the therapeutic potential of many NK cell surface receptors, have been illustrated (e.g., KIR, TIGIT, NKG2A, CD96, and PD-1), while those of many others remain to be shown (e.g., LAG-3 and TIM-3)." (PMID 32708748, 2020). "Consequently, blockade of TIGIT prevented NK cell exhaustion and enhanced NK cell-dependent tumor immunity in several CRC tumor-bearing mouse models." (PMID 33419310, 2020). "Currently, the physiological roles in tumor surveillance by NK cells, as well as the therapeutic potential, of many surface receptors on NK cells have been demonstrated (e.g., KIR, TIGIT, NKG2A, CD96, and PD-1), while those of many others still remain to be shown (e.g., LAG-3 and TIM-3)." (PMID 31552017, 2019). "Although the role of TIGIT and CD96 as immune checkpoint receptors are just beginning to be uncovered, accumulating data would support the notion that targeting of these receptors for improving anti-tumor immune responses also involves NK cells and ILCs." (PMID 31105707, 2019). "Unlike tumor-infiltrating T cells, almost no co-expression of PD-1 and TIGIT was observed on any of the TINK subsets." (PMID 30761123, 2019).
tumor (continued). "Tumour infiltrating lymphocytes (TILs) expressing TIGIT have been demonstrated in several tumour types such as nonsmall cell lung cancer, colorectal carcinoma, melanoma, and acute myeloid leukaemia." (PMID 30733837, 2019). "Clinically, TIGIT expression on tumor-infiltrating lymphocytes was shown to be elevated in GBM samples, suggesting that the TIGIT pathway may be a valuable therapeutic target." (PMID 30991686, 2019). "Expression of T-cell activation markers, CD69, ICOS and TIGIT, on tumor-infiltrating T-cells was not affected." (PMID 31747946, 2019). "As tumor numbers increased, immune checkpoints including PD-1, TIM-3, TIGIT, and CTLA-4 increased." (PMID 31801611, 2019). "Inhibition of some NK cell surface checkpoint receptors has displayed the potential to reverse NK cell dysfunction in tumors, and to boost anti-tumor immunity, both in clinical trials (anti-KIR and anti-NKG2A), and in preclinical studies (e.g., anti-TIGIT, and anti-CD96)." (PMID 31552017, 2019). "The tumor-associated expression pattern of TIGIT is not dependent on the adaptive immune system, since TIGIT was also highly expressed on tumor-infiltrating NK cells in SCID mice." (PMID 31552017, 2019). "These cells, when present, expressed co-inhibitory molecules, such as TIGIT and TIM-3, proportionally with the severity of the disease, thus suggesting an important role of the TME in reducing recruitment of functional NK cells to the tumor site." (PMID 32038612, 2019). "Importantly, EGFR-expressing OT-1 T cells injected into B16-OVA tumor bearing mice were recruited into the tumor, expressed lower levels of the exhaustion markers PD1, TIGIT, and LAG3, and were more efficient in delaying tumor growth." (PMID 31921216, 2019). "Thus, TIGIT and DNAM-1 can compete for binding to PVR and Nectin-2 which are highly expressed on tumour cells and are also upregulated by exposure to cytokines, such as IFN-γ and TNF-α." (PMID 30626155, 2019). "However, for targets such as CTLA-4, TIGIT, and VISTA, competent Fc is required for optimal anti-tumor immune responses in various mouse models." (PMID 30863404, 2019). "Similarly, to TIGIT and LAG3, the high expression of TIM-3 and PD-1 is observed in the tumor microenvironment, in particular on TIL and Treg, suggesting the possible re-establishing of T cell function through the targeting of TIM-3 and PD-1." (PMID 30991686, 2019). "In this study, we determined 11 immunomodulators that are involved in tumor escape mechanisms and found 9 immunomodulators (LAG-3, TIM-3, CTLA-4, IFN-γ, ICOS, ICAM-1, TIGIT, NKG2A, and VISTA) that were upregulated in both high-immune score group and high-stromal score group." (PMID 31781309, 2019). "However, the tumor-infiltrated Tregs include heterogeneous subsets of cells expressing different immunosuppressive molecules favoring tumor progression, such as CTLA-4, PD-1, LAG-3, TIM-3, and TIGIT." (PMID 30718502, 2019). "CD155 is the main ligand for TIGIT and CD96, and is highly expressed on many types of tumor cells." (PMID 30250471, 2018). "The results also showed that the percentage of total CD8+ cells increased and the more severely exhausted PD1+CTLA-4+CD8+, PD1+Tim-3+CD8+, PD1+TIGIT+CD8+, and PD1+LAG-3+CD8+ T cells in the tumour infiltrating CD8+ T-cell population decreased after vvDD-IL-2-RG treatment." (PMID 30410056, 2018). "We found that PD-1, CTLA-4, TIM-3, and LAG-3 were upregulated in tumor tissue, compared with normal tissue, while there was no change in PD-L1 and TIGIT." (PMID 29983831, 2018). "Since the knockout of intrinsic expression of TIGIT in tumor cells did not affect cell proliferation and colony formation, the tumor growth ability was examined in mice." (PMID 30555485, 2018). "Expression of alternative checkpoints such as LAG-3, TIGIT, TIM-3, and ICOS in the tumor microenvironment may also play a key role regarding clinical outcomes and are currently being explored." (PMID 30356816, 2018).
tumor (continued). "By treating NK cells with sd-rxRNA targeting inhibitory receptors such as TIGIT ex vivo, prior to ACT, the anti-tumor response of these cells may be enhanced resulting in a more effective therapy for hematological malignancies." (PMID 30400835, 2018). "Further, to explore the effects of tumor intrinsic TIGIT on CD8+ T cells without the existence of NK cells." (PMID 30555485, 2018). "One such molecule is T cell immunoreceptor with Ig and ITIM domains (TIGIT), which has been shown to be inhibitory and expressed by nonresponsive and suppressive T cells in the tumor microenvironment." (PMID 30400822, 2018). "Again, TIGIT−/− mice challenged with the same tumor models showed no significant reduction in numbers of tumor metastases in comparison with WT mice." (PMID 29868026, 2018). "The blockade effects on TIGIT expressed on tumor cells and immune cells has not been well distinguished." (PMID 30555485, 2018). "Our results on tumor-intrinsic TIGIT were similar to the current studies that TIGIT on NK and CD8+ T cells could suppress their anti-tumor effects." (PMID 30555485, 2018). "Blocking TIGIT interaction with its ligand CD155 can re-energize tumor antigen-specific CD8+ T cells, unleash NK cells and inhibit Treg-mediated immunosuppression in the tumor microenvironment." (PMID 30400822, 2018). "For example, CD8+ tumor-infiltrating lymphocytes exhibit high proliferation and IL-2/tumor necrosis factor (TNF)-α production in TC immunoreceptor with Ig and ITIM domain (TIGIT)−/− mice, indicating TIGIT inhibited the effector function and proliferation of CD8+ TC." (PMID 28738836, 2017). "In mouse tumor transplant models, treatment with TIGIT-blocking antibodies alone did not decrease tumor burden, but treatment with TIGIT blocking antibodies in combination with anti-PD-L1 or anti-PD-1 treatment brought about a robust anti-tumor response." (PMID 29211042, 2017). "However TIGIT inhibition of T cells seems mediated by CD226 disruption as CD226 blockade annihilates the curative impact of TIGIT and PD-L1 co-blockade on both tumor growth and chronic infection." (PMID 26347741, 2015). "The genomic background of CRC, including alterations in KRAS, NRAS, PIK3CA, AKT1, BRAF, and the tumor’s MSI status, may modulate both the abundance and biological relevance of the immune regulators TIGIT and CD155, thereby affecting immune evasion and clinical outcome." (PMID 41596586, 2026). "In silico analysis (Gene Expression Omnibus GSE127465) indicated that NECTIN2 was expressed in tumor cells, whereas TIGIT was predominantly expressed in T cells, suggesting that the NECTIN2/TIGIT axis may play a critical role in LUAD development and modulation of antitumor immune response." (PMID 40371640, 2025). "ICB resistance is driven by multiple factors, including T cell exclusion and dysfunction within the TME, defects in antigen processing, a lack of tumor-associated antigens, and the presence of alternative inhibitory immune checkpoints such as VISTA, TIM-3, LAG-3, and TIGIT." (PMID 40051497, 2025). "This interesting discovery was further confirmed by the in vitro coculture of tumor cells with activated CD8+ T cells, which revealed that the reconstituted H351Q cells promoted the exhausted status of CD8+ T cells, as indicated by the increased ratio of LAG3‐ and TIGIT‐positive cells." (PMID 39830021, 2025). "We assessed its co-expression with TIGIT, Tim-3, LAG-3, BTLA, and NKG2A across four groups: treatment-naïve CC patients and total CC patients, and peripheral CD8+ T cells from peripheral treatment-naive PBMCs versus tumor-infiltrating CD8+ T cells from biopsies of treatment-naive tumors." (PMID 41300994, 2025). "Overall, we delineated cell–cell interaction landscape of tumor cells and immune cells and revealed that Plac1+ tumor cells recruited CD4+ T cells through the CXCL11/CXCR3 axis and then induced Treg differentiation through PVR/TIGIT to shape the immunosuppressive TME of HNSCC." (PMID 40056047, 2025).
tumor (continued). "Notably, the proportion of TIGIT+PD-1+ double-positive CD8+ T cells was significantly elevated under co-culture conditions, indicating the acquisition of an exhaustion-like phenotype upon direct interaction with tumor cells." (PMID 40799645, 2025). "The down-regulation of immune-checkpoint receptors (PD1, CTLA4, TIGIT, etc.), up-regulation of cytokines (IFN-γ, TNF-α, IL2), and activation of granzyme and perforin, etc., remained the primary readouts to characterize the antitumor potential of tumor-infiltrated and activated T-cells." (PMID 40593750, 2025). "Similarly, ZGGS15, an IgG4 BsAb targeting LAG-3 and TIGIT, demonstrated potent anti-tumor efficacy without inducing ADCC, suggesting a safer and more effective approach." (PMID 40567374, 2025). "Then, in T-tumor co-culture scenarios, the in vitro QSP model can quantitatively and simultaneously predict the tumor cell killing dose response upon antibody treatments (mAbs and BsAbs) targeting different immune checkpoints such as TIGIT, PD-1, PD-L1 and TIGIT/PD-L1." (PMID 40276607, 2025). "Interestingly, expression of checkpoint inhibitors TIM3 and TIGIT (but not PD-1) on trNK cells increased closer to the tumor center." (PMID 40849493, 2025). "Furthermore, the expression of TIGIT is strongly correlated with NK cell exhaustion in CRC patients and tumor-bearing mice, and targeting the TIGIT signaling pathway in multiple tumor models has been shown to prevent NK cell exhaustion and enhance their antitumor immune responses." (PMID 40463500, 2025). "PVR/TIGIT, NECTIN2/CD226, and FAM3C/PDCD1 were relatively more strongly expressed in Plac1+ epi‐CD4+ T cells than Plac1− epi‐CD4+ T cells and PVR was specific for Plac1+ tumor cells, which was subsequently validated in HNSCC cells in vitro and in the TMA cohort by mIF." (PMID 40056047, 2025). "Hence, we assessed the tumor cell expression of four distinct immune checkpoint ligands; PD-L1, CD80, GAL-9, and PVR, which interact with the clinically relevant receptors PD-1, CTLA-4, TIM3, and TIGIT on T cells." (PMID 40108668, 2025). "Additionally, the absence of TIGIT expression in NK cells has been shown to delay tumor growth and improve survival." (PMID 40574024, 2025). "While anti-tumor T cell subsets, such as T_C1_Cytotoxic cells, were enriched in the low-PCD group, the high-PCD group exhibited a significant accumulation of exhausted T cells, characterized by the expression of exhaustion markers such as LAG3, HAVCR2, CTLA4, TIGIT, and CXCL13." (PMID 40740783, 2025). "Elevated TIGIT expression may contribute to an immunosuppressive tumor microenvironment by interacting with its ligands (e.g., PVR, NECTIN-2) expressed by stromal and malignant cells, thereby promoting T cell exhaustion and enabling tumor immune evasion." (PMID 40799645, 2025). "In NSCLC patients, tumor-infiltrating NK cells exhibit significantly elevated PD-1 expression, and these PD-1-positive NK cells concurrently coexpress multiple inhibitory receptors, including TIM-3, TIGIT, KIR2DL3, and KIR3DL1, resulting in compromised NK cell functionality." (PMID 40463500, 2025). "Interestingly, CD4 T cells in B16F10 tumours in Fgl2−/− mice were more CD25+ and TIGIT+." (PMID 38191799, 2024). "Comparatively, γδ T cells from patients that did not expand after treatment, did not have high expression of PD-1 or TIGIT, supporting the possibility that the expanded γδ cells in patient E-013 have received a γδ T cell-specific stimuli and were involved in the anti-tumor response." (PMID 38321065, 2024). "Preliminary studies have shown that simultaneously blocking TIGIT and either PD-1 or TIM3 promotes immune cell proliferation, cytokine release, and degranulation and reverses T-cell exhaustion, which in turn results in tumor rejection and protective memory responses 120,128." (PMID 38617537, 2024).
tumor (continued). "To further evaluate TIGIT-mediated tumor accumulation and overcome peripheral antigen sink, we repeated 89Zr-αTIGIT PET studies using a lower molar activity (higher antibody dose; 100 μg) and blocking dose (625 μg unconjugated anti-TIGIT) in mice with 1-week established GL261 tumors." (PMID 38438420, 2024). "These immunosuppressive cells express high levels of TIGIT, an immune checkpoint molecule, establishing cellular communication with various tumor cells (such as DUSP1_fib, BASP1_fib, PDGFRA_fib, and IDO1_fib) expressing NECTIN2, thereby facilitating immune evasion of the tumor cells." (PMID 38443340, 2024). "During tumor development and chronic viral infections, CD8 T-cells differentiate into an exhausted or dysfunctional state, which is accompanied by increased expression of inhibitory “immune checkpoint” receptors such as PD-1, LAG-3, TIM-3, CTLA-4, and TIGIT on the cell surface." (PMID 38788198, 2024). "The presence of the TIGIT–NECTIN2 interaction in both tumour types indicates that the activation of immunosuppressive ligand–receptor pairs in the TME is irrespective of the number of primary tumours." (PMID 39601163, 2024). "We next investigated whether these tumours had an infiltration of T cells (CD103, CD4, CD3, and CD8) and B cells (CD20) or expressed immune checkpoints (PD-L1, TIGIT, and LAG3) as these features are known to positively correlate with a response to immunotherapy." (PMID 38672534, 2024). "The anti-TIGIT antibody, anti-LAG-3 antibody, and anti-PD-1 antibody treatment groups could only slightly inhibit tumor growth, with mean tumor volumes of 446.66 ± 25.72 mm3 (TGI = 24.38%), 357.18 ± 63.73 mm3 (TGI = 44.40%), 374.64 ± 66.09 mm3 (TGI = 40.23%) respectively." (PMID 38724599, 2024). "However, the inhibitory effect of TIGIT was observed specifically on the CD8+ T‐cell‐mediated antitumour responses in tumour‐bearing mice, rather than NK cells, CD4+ T cells, or Tregs." (PMID 38279870, 2024). "Interestingly, Jia and colleagues proposed in their functional experiment studies in AML patients that TIGIT expression might be correlated with increased secretion of IFN-γ and TNF-α cytokines and granzyme B, supporting the NK anti-tumor activity in AML." (PMID 39339180, 2024). "Flt3L blockade did not have any effect on tumor growth or survival when administered alone, but tumor progression was controlled (p < 0.05) and survival was prolonged (p < 0.05) when combined with RT and anti-TIGIT treatment." (PMID 35794399, 2023). "In addition, the ligands of TIGIT, CD112 and CD155, are presented on tumor cells." (PMID 37510993, 2023). "Compared with WT Tregs, however, SRC-3 KO Tregs do not have heightened immune suppressive functions in the tumor microenvironment due to the down-regulation of many genes involved in immune suppression such as T Cell Immunoreceptor With Ig And ITIM Domains (TIGIT) and others." (PMID 37253006, 2023). "Moreover, anti-α-TIGIT scFv expression and secretion interrupted the interaction between TIGIT and its ligand CD155, enhancing the infiltration and activation of CAR-T cells in the TME to achieve increased tumor regression in vivo." (PMID 37670328, 2023). "Moreover, in contrast to the “DB + anti-PD-L1” mice, the differences in tumor growth between the DB and DB + anti-TIGIT experimental groups were found, from day 16, to be no longer statistically significant." (PMID 37444427, 2023). "We have developed multispecific antibodies targeting PD-L1, TIGIT, and LAG-3 and evaluated them with carefully designed in vitro and in vivo assays, which show that these antibodies efficiently promote T cell activation and cancer cell killing and suppress tumor growth." (PMID 37332070, 2023). "CTLA-4, TIGIT and KLRG1 may thus contribute to the reduced anti-tumor activity in aging mice." (PMID 37752597, 2023).